FABP4 (fatty acid binding protein 4)
Diseases named in the same sentence as FABP4 in open-access papers (continued):
Sharing a sentence is not in itself a finding about the gene and the disease.
prostate carcinoma (continued). "The relevance of FABP4 in prostate cancer has recently been identified." (PMID 36060264, 2022). "It has been proved that FABP4 treatment could promote prostate cancer cell invasion in a significant study in vitro, and this boosting effect was remarkably reduced by the FABP4 inhibitor." (PMID 36060264, 2022). "Fatty acid-binding protein 4 (FABP4) released from adipocytes could promote invasion in prostate cancer." (PMID 35664768, 2022). "Similarly, bone marrow adipocytes promote bone metastasis formation in prostate cancer, which is, in part, mediated through the PPARγ-induced activation of fatty-acid-binding protein 4 (Fabp4)." (PMID 35954274, 2022). "For prostatic cancer, contradicting evidence has been described about the role of FABP4." (PMID 32856199, 2020). "Together, these results indicate AR may enhance prostate cancer growth and survival by suppressing the induction of FABP4 by PPARγ." (PMID 29181019, 2017). "We gratefully acknowledge Dr. Kenneth Pienta (Johns Hopkins, MD) for providing TMAs from prostate cancer patients for immunohistochemical analyses of FABP4 expression and Dr. Dong Ping Shi (WSU, Karmanos Cancer Institute) for histopathological evaluation of TMAs." (PMID 24240026, 2013). "Associated with this decrease is a significantly lower expression of adipocyte-related genes such as adiponectin, FABP4 and resistin, a result in agreement with previously reported evidence of prostate cancer cells invasion and destruction of adipocytes within a primary human bone marrow stroma." (PMID 24240026, 2013). "Thus, FABP4 plays an essential role in the progression of HF-mediated prostate cancer through the modulation of metabolic and inflammatory pathways, providing a potential therapeutic target for prostate cancer." (PMID 41226657, 2025). "Studies utilizing BMA-enriched mouse models found upregulated levels of FABP4 in Prostate Cancer(PCa) cells directly in contact with BMAs, suggesting a bidirectional interaction between FABP4 and the PPARγ pathway may enhance the invasiveness of tumor cells in bone metastasis." (PMID 38571500, 2024). "However, the role of FABP4 in prostate cancer remains controversial." (PMID 36060264, 2022). "Strong expression of FABP4 could also be detected in prostate cancer with skeleton metastasis." (PMID 30013512, 2018). "Additionally, fatty acid transfer from marrow adipocytes could stimulate invasion of prostate cancer cells, which is decreased upon inhibition of FABP4." (PMID 28915700, 2017). "Another promising FABP4 inhibitor, BD62694, exhibited efficacy by reducing the tumour burden and lung metastasis in prostate cancer." (PMID 38610991, 2024). "In GO/KEGG analyses, we found indirect roles of FABP4 in the PI3K-Akt signaling pathway, prostate cancer, AMPK, and PPAR signaling pathways." (PMID 36532833, 2022). "Of the fatty acid binding proteins (FABPs) present in mammalian tissues, FABP4 and cutaneous FABP (FABP5) have been extensively studied in prostate cancer." (PMID 29181019, 2017). "FABP4+ prostate cancer cells were significantly more invasive as compared to cells treated with a FABP inhibitor, and treatment with a fatty acid, oleic acid, was able to further enhance the invasiveness of FABP4+ prostate cancer cells." (PMID 39596205, 2024). "With the 5-gene prostate cancer metastasis signature panel comprised of U2AF2, RUVBL1, STMN1, HDGF, and FABP4, we further assessed the power of prediction of this gene signature panel in two different, independent public patient datasets (Grasso CS, Nature, 2012; Varambally S CS, Cancer Cell, 2005)." (PMID 39402324, 2024). "In addition, FABP4 promotes tumor progression by altering the activities of matrix metalloproteinases (MMPs), especially MMP-2 and MMP-9, in prostate cancer." (PMID 34685761, 2021).
prostate carcinoma (continued). "FABP4, an abundant protein in adipocytes that is influenced by a HFD or obesity, may enhance prostate cancer progression and invasiveness by upregulating matrix metalloproteinases and cytokine production in the prostate cancer stromal microenvironment." (PMID 31052319, 2019). "Thus, the CRABP-II promoter harbors a consensus RARE, the expression of FABP4 is directly regulated by PPARγ in adipocytes, and, as shown here, FABP5 is a direct target gene for PPARβ/δ in prostate cancer cells." (PMID 20847935, 2010). "Furthermore, overexpression of FABP4 by transfection in prostate cancer cell lines induces apoptosis by decreasing transforming growth factor-alpha activity and upregulating the expression of TNF-α, indicating a possible contribution of FABP4 in tumor suppression." (PMID 36060264, 2022). "Studies on the prostate cancer cell line DU145 revealed that FABP4 was not expressed in cells; subsequent introduction of FABP4 into DU145 cells revealed that the proliferation was significantly inhibited." (PMID 34558731, 2021). "FABP4 could additionally activate the phosphatidyl-inositol 3-kinase (PI3K)/AKT tumor pathway, participating in tumor growth and survival without being assimilated by prostate cancer cells." (PMID 36060264, 2022).
hepatocellular carcinoma (30 papers, 2018 to 2025). A malignant tumor that arises from hepatocytes. "While in contrast, FABP4 exhibited an antitumour effect on hepatocellular carcinoma cells and was associated with favourable prognosis of patients." (PMID 35198079, 2022). "Data from several cell culture and animal model experiments identified FABP4 as a potent tumor promoter in ovarian, prostate, cholangiocellular, and hepatocellular cancer." (PMID 37874427, 2024). "For this reason, the reduction or inhibition of FABP4 has been proposed as a promising therapeutic approach for MAFLD or end-stage liver disease such as hepatocellular carcinoma." (PMID 36769659, 2023). "Exogenous FABP4 stimulates tumor cell growth and migration in a number of different cancers, including hepatomas." (PMID 36358315, 2022). "FABP4 suppresses the proliferation and invasion of hepatocellular carcinoma cells and is a predictor of poor prognosis." (PMID 36114448, 2022). "The expression of FABP4 in hepatocellular carcinoma (HCC) tissues is lower than that in the adjacent tissue." (PMID 36532833, 2022). "The expression of FABP4 in hepatocellular carcinoma tissues was lower than that in the corresponding paracancerous tissues." (PMID 36532833, 2022). "Actually, in vitro studies showed that exogenous FABP4 significantly increased the proliferation and migration of human hepatocellular carcinoma cells." (PMID 35052876, 2022). "On the other hand, the serum FABP4 levels have been found increased in patients with hepatocellular carcinoma, thereby suggesting a pivotal role as a potential biomarker not only for MAFLD, but also for end-stage liver disease." (PMID 35052876, 2022). "This cross talk between LSEC and hepatoma cells was mainly mediated by FABP4-enriched microvesicles released from endothelial cells." (PMID 33198153, 2020). "Nevertheless, incubation of hepatoma cell lines with free fatty acid treatment led to FABP4 release into the medium." (PMID 30575815, 2019). "In contrast, FABP4 plays an oncogenic role in hepatocellular carcinoma, promoting proliferation and migration via downregulation of the HIF1 pathway." (PMID 31803141, 2019). "A previous study proposed that FABP4 suppresses hepatocellular carcinoma cell proliferation and invasion in vitro and decreases tumor volume in vivo, suggesting that FABP4 could be a potential therapeutic target for cancer." (PMID 39353883, 2024). "Additionally, exposure of human hepatoma cells to exogenous FABP4 stimulates FFA accumulation, cell proliferation, and cell migration." (PMID 36358315, 2022). "In contrast, FABP4 exhibited an antitumour effect on hepatocellular carcinoma cells." (PMID 35198079, 2022). "Similarly, it was demonstrated that in hepatocellular carcinoma an increase of FABP4 is accompanied by a decrease of tumor growth and invasiveness." (PMID 32856199, 2020). "Interestingly, de novo expression of LSEC FABP4 in response to exposure to glucose, insulin or hypoxia potentiates the oncogenic effects of hepatoma cell lines (HepG2, SKHep1, and Huh7) through activation of mechanistic target of rapamycin (mTOR) pathway." (PMID 33198153, 2020). "In addition to VEGFA, we demonstrated that hypoxia, a condition increasing VEGFA expression, also upregulates FABP4 as well as in hepatoma cell lines." (PMID 30575815, 2019). "Thus, downstream effectors of related pathways remain to be discovered, and FABP4 may play different roles in the metastasis and/or progression of hepatocellular carcinoma." (PMID 36532833, 2022). "In hepatocellular carcinoma (HCC), FABP12 forms a gene cluster with FABP4, FABP5, FABP8, and FABP9, which is frequently co-amplified." (PMID 40717587, 2025). "Increasing evidence suggests that FABP4 reduction/inhibition may be considered as a promising therapeutic approach for both MAFLD and end-stage liver disease such as hepatocellular carcinoma." (PMID 35052876, 2022).
hepatocellular carcinoma (continued). "While no basal expression of FABP4 was observed in hepatoma cell lines, we evaluated the effect of hypoxia (a common feature of malignancy) on FABP4 expression in HepG2 and HuH7 cells." (PMID 30575815, 2019). "The latest research revealed that LPL/FABP4/CPT1, a fatty acid metabolism reprogramming axis, was significantly upregulated in nonalcoholic steatohepatitis (NASH) and cooperated with a large number of oncogenic signals to drive NASH to directly progress to hepatocellular carcinoma." (PMID 36254139, 2022). "Thus, although hepatoma cell lines do not express FABP4, stimulation of hepatoma cell lines with eFABP4 modulated several molecular mechanisms involved in tumor progression, including angiogenesis and the cell cycle." (PMID 30575815, 2019). "We did not observe FABP4 expression in hepatoma cell lines (HepG2, SKHep1 and HuH7)." (PMID 30575815, 2019). "In hepatocellular carcinoma (HCC), FABP9 co-amplifies with other FABP family members (e.g., FABP4, FABP5), which may synergistically promote lipid metabolic reprogramming and tumor progression." (PMID 40717587, 2025).
colon cancer (28 papers, 2020 to 2026). "Our findings revealed a significant elevation in the levels of both FFA transporters in high-grade CRC tissues, which aligns with previous reports indicating that CD36 and FABP4 play a role in promoting colon cancer metastasis and are associated with a poor prognosis." (PMID 38245780, 2024). "It has been found that higher lipid accumulation and stronger FABP4 transcripts were observed in colon cancer tissues." (PMID 40595026, 2025). "When incubated with adipose tissue extracts and overexpressed FABP4, colon cancer cells exhibited enhanced lipid accumulation and significantly enhanced invasion and migration." (PMID 40595026, 2025). "In FABP4-overexpressing colon cancer cells, the expression of the AKT pathway and epithelial-mesenchymal transition (EMT)-related proteins was regulated." (PMID 40595026, 2025). "Overexpression of FABP4 promotes cell migration and invasion of colon cancer, which is consistent with our study." (PMID 36890467, 2023). "FABP4 overexpression can affect the metabolism of colon cancer cells and promote their migration and invasion." (PMID 37260987, 2023). "It was recently discovered that FABP4 promotes the metastasis and invasion of colon cancer and that the treatment with a classical small molecule inhibitor (BMS309403) weakened the migration and invasion of colon cancer cells." (PMID 36355506, 2022). "A recent study showed that FABP4 triggers invasion and metastasis in colon cancer through the regulation of fatty acid transport." (PMID 36114448, 2022). "Pharmaceutical inhibition of FABP4 reversed the effects of the adipocyte co-culture, and conversely when FABP4 was overexpressed in colon cancer cells, significant increases in metastases were observed in vivo." (PMID 33498240, 2021). "In colon cancer, FABP4 enhances epithelial–mesenchymal transition and the associated proteins, including MMP-2, MMP-9, and E-cadherin via the AKT pathway." (PMID 34685761, 2021). "At the same time, we verified the overexpression of FABP4 at mRNA and protein levels in colon cancer cells and found that lipid accumulation was more obvious in FABP4-overexpressed HCT-116 cells compared with control group." (PMID 33088219, 2020). "Overall, these results indicated that FABP4 enhanced the EMT in colon cancer cells, probably through AKT pathway." (PMID 33088219, 2020). "The distribution of lipids and FABP4 was tested in the colon cancer tissues and adjacent normal tissues, and their relationship was also verified in vitro." (PMID 33088219, 2020). "Both the CSCC and colon cancer studies further indicate that extracellular FABP4 is responsible for promoting EMT and metastasis through tumor–stroma interaction." (PMID 33352874, 2020). "In our study, the EMT phenotype markers changed significantly in FABP4-overexpressed colon cancer cells: the upregulation of Snail, MMP-2 and MMP-9, as well as the downregulation of E-cadherin." (PMID 33088219, 2020). "In our study, we found that the transcription level of FABP4 in colon cancer tissues was significantly increased, indicating the enhanced lipogenesis ability of colon cancer." (PMID 33088219, 2020). "There is also a recent study linking FABP4 to colon cancer invasion and metastasis, with FABP4 triggering the EMT program and lipid-related energy production." (PMID 33352874, 2020). "The results above indicated that lipid accumulation in colon cancer cells was related to FABP4-mediated FA transport through the transmembrane, a process that promotes lipogenesis." (PMID 33088219, 2020). "The results above indicated that adipose extract enhanced energy metabolism and lipid metabolism of colon cancer cells, but this effect was reversed by FABP4 inhibitor, suggesting that FABP4 promoted tumor metabolism." (PMID 33088219, 2020). "Higher accumulation of lipids and stronger FABP4 transcription were observed in colon cancer tissues." (PMID 33088219, 2020).
colon cancer (continued). "The EMT was significantly enhanced in FABP4-overexpressed colon cancer cells, as evidenced by the upregulation of Snail, MMP-2 and MMP-9, and the downregulation of E-cadherin." (PMID 33088219, 2020). "Having been incubated with adipose tissue extract and overexpressed FABP4, colon cancer cells demonstrated enhanced lipid accumulation." (PMID 33088219, 2020). "Future studies are needed to further determine the role of FABP4 in regulating cancer stemness in colon cancer." (PMID 32913185, 2020). "The results in vivo were consistent with the in vitro data, showing that FABP4 promoted colon cancer metastasis." (PMID 33088219, 2020). "In functional experiments, co-culture with adipose tissue extract significantly enhanced the invasion and migration of colon cancer cells, as well as the energy and lipid metabolism, and all these processes were reversed by FABP4 inhibitor." (PMID 33088219, 2020). "In our study, we found the transcription level of FABP4 mRNA in colon cancer tissues was 3.17 ± 0.38 times of that in adjacent normal tissues (P < 0.05)." (PMID 33088219, 2020). "Experiments about cellular invasion, migration and proliferation were performed to detect the impacts of FABP4 on the biological behaviors of colon cancer, and the positive results were checked in vivo." (PMID 33088219, 2020). "In co-culture + inhibitor group, the “wound” width was 1.86 ± 0.02 times of that in co-culture group (P < 0.05), which means FABP4 inhibitor suppressed the increased migration of colon cancer cells." (PMID 33088219, 2020). "In our study, we found the level of p-Akt was up-regulated in colon cancer cells with FABP4 overexpression." (PMID 33088219, 2020). "In co-culture + inhibitor group, the number of transmembrane cells was 31.45% of that in co-culture group (P < 0.05), which means FABP4 inhibitor suppressed the increased invasion of colon cancer cells." (PMID 33088219, 2020). "Thus, it is suggested that FABP‐4 enhances the invasiveness, migration, and metastasis of colon cancer cells." (PMID 40857027, 2026). "ALOXE3, PPARGC1A or FABP4 are prognostic biomarkers in colon cancer." (PMID 37055842, 2023). "In addition, expression levels of IGKV1-6, IGLV6-57, and CCL28 were higher in colon cancer, while VIP and FABP4 were more biased to be expressed in high-risk group." (PMID 36890467, 2023). "In another study, FABP4 was similarly highly expressed in colon cancer tissues." (PMID 35479956, 2022). "Indeed, in vitro co-culture experiments revealed increased FABP4 expression and lipid accumulation coupled with altered metabolism, invasion, and migration of colon cancer cells." (PMID 33498240, 2021). "However, how FABP4 regulates EMT downstream signaling cascades in colon cancer cells needs to be resolved with further experiments." (PMID 33088219, 2020). "To further explore the relationship between FABP4 and colon cancer, we observed that the synthesized EGFP-tagged FABP4 protein could be taken up by colon cancer cells." (PMID 33088219, 2020). "Immunofluorescence verified that the FABP4 protein could be taken up by colon cancer cells, and its overexpression significantly enhanced the lipid accumulation." (PMID 33088219, 2020). "The differentially expressed genes in FABP4-overexpressed colon cancer cells were analyzed." (PMID 33088219, 2020). "In addition, the metastasis of FABP4-overexpressed colon cancer cells was also significantly enhanced in vitro and in vivo." (PMID 33088219, 2020). "Finally, FABP4 overexpression improved EMT progression of colon cancer, as evidenced by the upregulation of Snail, MMP-2 and MMP-9, the downregulation of E-cadherin." (PMID 33088219, 2020). "The present study proved, for the first time, the effects of adipocyte-derived FABP4 on the metastasis of colon cancer cells and the related mechanisms, which may provide a new potential therapeutic target against colon cancer progression." (PMID 33088219, 2020).